HIF1A (hypoxia inducible factor 1 subunit alpha)
Diseases named in the same sentence as HIF1A in open-access papers (continued):
Sharing a sentence is not in itself a finding about the gene and the disease.
pancreatic cancer (continued). "Here we found that tamoxifen promotes multiple changes in PSCs and the microenvironment of pancreatic cancer through a GPER‐dependent mechanism that induces a negative regulation of HIF‐1A by decreasing actomyosin‐dependent PSC contractility and matrix stiffness mechanosensing." (PMID 30538116, 2019). "Treatment with Fuco-MnO2-NPs and PAH-MnO2-NPs, but not fucoidan alone, clearly suppressed hypoxia-induced HIF-1α expression or hypoxia-responsive luciferase activity in pancreatic cancer cells, indicating that the Fuco-MnO2-NPs alleviated the hypoxic condition via the generation of oxygen." (PMID 30558324, 2018). "In our present study, we identified TCF7L2 as a novel predictive marker for OS of pancreatic cancer patients, and we provided mechanisms for the metabolism effects, indicating a potential role for TCF7L2 in aerobic glycolysis regulation by targeting the EGLN2/HIF-1α axis." (PMID 29476053, 2018). "However, knockdown of HIF-1α or HIF-2α did not affect the TRAIL sensitivity of two other human pancreatic cancer cell lines, CAPAN-2 and CFPAC-1 (data not shown)." (PMID 28476028, 2017). "However, unlike the well-studied hif-1α, the role of hif-2α in tumors, including pancreatic cancer, is poorly understood." (PMID 28705232, 2017). "However, to the best of our knowledge, the mechanism of HIF-1α-mediated BNIP3 induction in pancreatic cancer cells has not yet been fully elucidated." (PMID 28968982, 2017). "The absence of BNIP3 expression in pancreatic cancer cells was related to gene methylation that suppressed binding of HIF-1α to the BNIP3 promoter, whereas 5-Aza-2′-deoxycytidine (Aza-dC) treatment restored BNIP3 expression and sensitized pancreatic cancer cells to BNIP3-induced apoptosis." (PMID 28968982, 2017). "Moreover, HIF-1α expression and β2-AR expression are positively correlated with smoking status, different histological differentiation and among the tumor node metastasis (TNM) stages in pancreatic cancer patients." (PMID 26497365, 2016). "HIF-1α expression is commonly upregulated in a lot of malignant tumors, and many publications have reported the close correlation between HIF-1α expression and increased aggressiveness and higher metastatic capacity in ovarian, breast, lung, prostate, colon and pancreas carcinomas." (PMID 26057751, 2015). "The expression of HIF-1α might be activated by AKT phosphorylation, as we previously reported, whereas the over-expression of CypA might stimulate the proliferation of human pancreatic cancer cells by activating the ERK1/2 and p38 pathways." (PMID 24662981, 2014). "In intermittent hypoxia knockdown of HIF-1α expression in non-stem pancreatic cancer cells by siRNA with or without 3-methyl adenine (3-MA), the inhibitor of autophagy, it was easily found that the cell morphology changed a spread fibroblast-like into an epithelial-like appearance." (PMID 24305593, 2013). "Finally, we tested the relation among HIF-1α, autophagy and the conversation of non-stem pancreatic cancer cells into pancreatic CSCs." (PMID 24305593, 2013). "The present study focuses on whether non-stem pancreatic cancer cells can convert to stem-like cells and the role of HIF-1α and autophagy in modulating this conversation." (PMID 24305593, 2013). "It has also been observed that the exposure of human MIA-PaCa-2 pancreatic cancer cells expressing high levels of CD44 and CD24 stem cell-like markers to hypoxia and nutrient starvation induced the EMT programme and the expression of HIF-1α and autophagy-related genes." (PMID 23301832, 2013). "Taken together, these findings suggested that the HIF1α-mediated hypoxic signal pathway contributes to MUC17 expression, and DNA methylation of HRE could be a determinant of the hypoxic inducibility of MUC17 in pancreatic cancer cells." (PMID 22970168, 2012).
pancreatic cancer (continued). "Interestingly, in pancreatic tumors lacking HIF‐1α, hypoxia leads to glycogen accumulation and the secretion of IL‐1β and IL‐8, which recruit proangiogenic cDC1 and cDC2 subsets, demonstrating an HIF‐1α‐independent mechanism of immune modulation and tumor progression." (PMID 40667699, 2025). "Furthermore, another study reported that under hypoxic conditions, HIF-1α induces the expression and secretion of hepatocyte growth factor in pancreatic stellate cell, which in turn activates Met and the PI3K-AKT pathway, leading to resistance to EGFR inhibitor in pancreatic cancer." (PMID 37460927, 2023). "Indeed, copper chelation in the RIP-Tag model of pancreatic cancer, expressing the SV40T oncogene under control of the rat insulin promoter, and in human endometrial cancer cells resulted in Complex IV inactivation and HIF-1α stabilization or inhibition of SOD163." (PMID 34911956, 2021). "Thus, inflammation and/or other factors in the tumor microenvironment may affect both Mint3 and HIF-1α expression in pancreatic cancer, and co-overexpressed Mint3 and HIF-1α might further induce SKP2 overexpression and thereby promote pancreatic cancer progression." (PMID 32826949, 2020). "Besides, the study indicated HIF-1α bound to the regulatory region in the upstream of the initiation codon of retention in endoplasmic reticulum 1 (RER1) and increased its transcriptional activity, enhancing pancreatic cancer stem cells properties and inducing EMT." (PMID 32587480, 2020). "However, the interaction between HIF-1α and SCF in pancreatic cancer remains unclear." (PMID 25799412, 2015). "Next, we examined the sensitivity of these cell lines to TRAIL and found that siRNA-mediated knockdown of HIF-2α, but not HIF-1α, significantly decreased the cell viability of the TRAIL-treated three pancreatic cancer cell lines under hypoxic conditions." (PMID 28476028, 2017). "In this study, we validated Pfn1 as a tumor-suppressor in pancreatic cancer, and identified a novel mechanism of PFN1 regulation of the SIRT3- HIF1α axis, independent of its cytoskeleton-related activity." (PMID 25103363, 2014). "Previous studies suggest that HIF-1α activates pro-fibrotic factors (e.g., connective tissue growth factor, CTGF), but its relationship with the TGF-β1 pathway has not been systematically explored in pancreatic cancer." (PMID 40406267, 2025). "Emerging evidence indicates that HIF-1α may enhance TGF-β1/Smad pathway activity through non-canonical routes (e.g., PI3K/Akt), yet the role of this mechanism in pancreatic cancer ECM regulation remains uncharacterized." (PMID 40406267, 2025). "IL-37 expression was decreased in pancreatic cancer, down-regulated IL-37-mediated gemcitabine resistance via interacting with HIF-1α and signal transducer and activator of transcription 3 (STAT3) and forming the HIF-1α/IL-37/STAT3 negative feedback." (PMID 32587480, 2020). "In this study, we examined the effects of HIFs on the TRAIL sensitivity of a panel of human pancreatic cancer cell lines and found that knockdown of HIF-2α, but not HIF-1α, increased TRAIL sensitivity in five out of the seven pancreatic cancer cell lines evaluated." (PMID 28476028, 2017). "Moreover, pancreatic cancer cells in smokers express higher levels of HIF-1α than in non-smokers, and high HIF-1α expression is correlated with low degree of histological differentiation and high TNM stages in human pancreatic cancer." (PMID 26497365, 2016). "Similarly, embryonic stem cells and pancreatic cancer cells under hypoglycaemia induced HIF target gene expression in a manner dependent on the HIFα dimerisation partner ARNT, but independent of HIF-1α." (PMID 20637078, 2010). "Given that cancer cells, even under non-hypoxic conditions, are capable of inducing HIF-1α and can actively shift their energy production from mitochondrial to glycolytic sources 44, our data suggest that treatment of oxLDL mimics a 'Warburg'-like effect in KLM-1 pancreatic cancer cells." (PMID 34475995, 2021).
pancreatic cancer (continued). "Similarly, based on this negative loop, in pancreatic cancer, HIF-1α-induced miR-646 expression was shown to target migration and invasion inhibitory protein (MIIP) to inhibit the deacetylation ability of HDAC6, which eventually promoted the acetylation and proteasomal degradation of HIF-1α." (PMID 32014012, 2020).
colorectal cancer (388 papers, 2008 to 2026). A primary or metastatic malignant neoplasm that affects the colon or rectum. "Of greater significance, ncRNAs are capable of engaging with the hypoxic tumor microenvironment, a hallmark of solid tumors, particularly with HIF-1α, to synergistically modulate the progression of colorectal cancer." (PMID 40305214, 2025). "For example, TRAF6 binds HIF-1α and mediates its K63-linked polyubiquitination, maintaining HIF1α’s stability and promoting colorectal cancer development." (PMID 38769340, 2024). "Mutations in the VHL gene are common in colorectal carcinoma and result in the accumulation of HIF1α, leading to tumor angiogenesis." (PMID 38769340, 2024). "In colorectal cancer, HIF1A, MMP9, and PTGS2 had the highest mutation frequency at 5.8%, 7.7%, and 5.8%, respectively, while in melanoma, PPARG and TGFB1 had the highest mutation frequency at 4.7% and 1.9%, respectively." (PMID 37033970, 2023). "had reported that Brusatol-mediated inhibition of c-myc increases HIF-1α degradation and causes cell death in colorectal cancer under hypoxia." (PMID 35211403, 2022). "The anti-colorectal cancer effects of cryptotanshinone can be caused by the downregulation of HIF-1α and VEGF levels in vivo." (PMID 34575983, 2021). "Recently, metabolic targeting of HIF-1α has been shown to potentiate chemotherapy responses in human colorectal cancer tumor growth in a murine model, which was associated with reduced angiogenesis." (PMID 33142239, 2020). "Overexpression of HIF-1α was observed in various human cancers, including colorectal cancer and is independently associated with poor prognosis." (PMID 33142239, 2020). "Many studies have reported associations between HIF1A polymorphisms and the risks of various types of cancer, including bladder, oral, and colorectal cancers, head and neck squamous cell carcinoma, and renal cell carcinoma." (PMID 31744467, 2019). "The role of Tip60 in HIF-1α activation has been implicated in hypoxia based on the expression of HIF-1α-dependent genes in colorectal cancer cells." (PMID 31671779, 2019). "In colorectal cancer, hypoxia-inducible factor (HIF-1α) and cancer-associated fibroblasts (CAFs)-secreted TGF-β2 converge to induce strong expression of GLI2 in CSCs, independently of HH signaling." (PMID 31244888, 2019). "Little is known about the correlation between HIF-1α and IL-6 in sepsis, however, in colitis-associated colorectal cancer serum concentrations of IL-6 positively correlated with HIF-1α mRNA levels in the tumor tissue." (PMID 30524296, 2018). "Recently, it was also reported that the expression of NHERF1 was strongly correlated with higher expression of HIF-1α in colorectal cancers, suggesting association with the tumor hypoxia microenvironment." (PMID 27999191, 2017). "miRNA-31 contributes to colorectal cancer development by targeting factorinhibiting HIF-1α (FIH-1), and miR-31 is closely associated with the colorectal cancer stage." (PMID 27793031, 2016). "Clinically, the tissue microarray (TMA) analysis discloses the negative regulatory association between RPS7 and HIF-1α in colorectal cancer." (PMID 26735579, 2016). "To verify our assumption, we took colorectal cancer and its associated robust genes HIF1A and MLH as an example." (PMID 24350280, 2013). "We suppose that this HIF-1α activation is associated with the stepwise progressive genetic instability during colorectal cancer development." (PMID 18983642, 2008).
colorectal cancer (continued). "Moreover, ectopic expression of PHD1 suppressed accumulation of HIF1α, which has been—when overexpressed—associated with mortality in colorectal cancer patients." (PMID 36976352, 2023). "HIF-1α was shown to synergize with Transforming growth factor-2 released by cancer-associated fibroblasts to promote GLI family zinc finger 2 expression in colorectal cancer stem cells (CSCs), resulting in enhanced stemness, dedifferentiation, and chemotherapy resistance." (PMID 37460927, 2023). "Furthermore, shikonin causes the suppression of HIF-1α under hypoxia, resulting in efficient restraint of in vitro proliferation and in vivo growth of colorectal cancer cells." (PMID 34575983, 2021). "In addition, a decreased level of ROS in colorectal cancer cells is known to suppress the accumulation of HIF-1α caused by free radicals, thereby inhibiting their development." (PMID 33052979, 2020). "Overall, we reveal that RPS7 inhibits colorectal cancer glycolysis through HIF-1α-associated signaling and may be a promising biomarker for prognosis prediction and a potential target for therapeutic treatment." (PMID 26735579, 2016). "Furthermore, the expression of HIF-1α has been also associated with resistance to 5-fluorouracil and oxaliplatin, two commonly used drugs in standard care of colorectal cancer." (PMID 24932611, 2014). "HIF1A associated with colorectal cancer is one of robust genes." (PMID 24350280, 2013). "We hypothesized that Annexin A3, a member of the Annexin family, and HIF-1α may be associated with each other in colorectal cancer." (PMID 24260057, 2013). "Since a strong association between nuclear expression of HIF-1α and severe peritumoral inflammation was observed in situ, the question arises whether LPS stimulation of colorectal carcinoma cell lines leads to up-regulation of this transcriptional factor." (PMID 18983642, 2008). "Furthermore, in colorectal cancer cells, SN-38 may suppress HIF-1α and VEGF to cause cell cycle arrest in the S and G2/M phases, which elevates radiosensitivity." (PMID 37460927, 2023). "In terms of tumor biology, this review synthesizes pan-cancer analysis data to summarize the expression patterns of HIF-1α in major gastrointestinal malignancies, including esophageal, gastric, pancreatic, hepatocellular, and colorectal cancers." (PMID 41988193, 2026). "In colorectal cancer, piR-823 fosters invasion by stabilizing HIF-1α and G6PD, correlating with poor prognosis." (PMID 42022287, 2026). "In this study, we used a differential expression model of HOTAIR in colorectal cancer cells to evaluate the role of this lncRNA in metabolic reprogramming and its potential interaction with HIF-1α." (PMID 40072116, 2025). "Lee M. Ellis has illuminated the complex molecular alterations occurring within chemoresistant colorectal cancer cells, specifically concerning intracellular ATP stability regulation and its effects on HIF-1α, a crucial mediator of drug resistance 42,43." (PMID 41209562, 2025). "In colorectal cancer, the transcriptional activity and stability of HIF‐1α were also reported to be regulated by 14‐3‐3σ." (PMID 40515512, 2025). "In conclusion, this study systematically reveals for the first time that Curcumol inhibits glycolysis and colorectal cancer (CRC) progression by activating the VHL/HIF-1α signaling axis." (PMID 41008845, 2025). "Overexpressed 5′ tiRNA-His-GTG in colorectal cancer is regulated by hypoxia-inducible factor 1 alpha (HIF1α)/ANG under hypoxic conditions." (PMID 40247912, 2025).